CDKN3 (cyclin dependent kinase inhibitor 3)
Diseases named in the same sentence as CDKN3 in open-access papers (continued):
Sharing a sentence is not in itself a finding about the gene and the disease.
tumor (continued). "Furthermore, upregulation of has-miR-181d-5p or silencing/inhibiting CDKN3 demonstrated inhibition of cellular proliferation, increased apoptosis, inhibition of cellular migration/invasion, repression of the Akt signaling pathway, and inhibiting tumor growth in mice." (PMID 37682177, 2023). "The results revealed that AURKA, BIRC5, CCNB1, CDK1, CDKN3 and TYMS were significantly upregulated in tumor tissues." (PMID 37393234, 2023). "Based on the gene expression data retrieved from the TCGA database, 4 of the 20 DEmRNAs (CAP2, CDKN3, MELK and UBE2T) were upregulated in tumor tissues, and the remaining DEmRNAs were upregulated in adjacent normal tissues." (PMID 33879119, 2021). "Several important cell cycle regulators were found differentially expressed in the reprogrammed tumours, including CDK4, E2F5, and CDKN1B (P27), WEE1, CDKN3." (PMID 29662623, 2018). "Is it because the relationship between NOTCH and CDKN3 is not as close as we analyzed, or is it because of sample size, tumor type, or statistical errors that have led to bottlenecks in related research?" (PMID 38720365, 2024). "In addition, the methylation expression level of CDKN3 was significantly increased in ESCA, KIRC, LUSC, and PAAD tumor tissues." (PMID 38720365, 2024). "Upregulated ZNF677 significantly inhibits CDKN3 (cyclin-dependent kinase inhibitor 3) at both mRNA and protein levels, inhibiting tumor growth and inducing cell apoptosis, exerting a negative impact on RCC progression." (PMID 38202722, 2023). "In order to explore the potential function of CDKN3 in RCC, we analysed the expression of CDKN3 in RCC tissues and noncancerous normal tissues, and found that CDKN3 is frequently elevated in tumour tissues from the TCGA database." (PMID 35678231, 2022). "In vitro and clinical data confirm the negative roles of ZNF677/CDKN3 in tumour growth and progression of RCC." (PMID 35678231, 2022). "The tumor markers CDKN2A and KRT7 were the most upregulated genes with fold changes 10.7 and 4.8, respectively, while markers for proliferation (MELK, CDK1, MKI67, CCNB2, BUB1, FOXM1, CDKN3) had fold changes spanning from 2.0–2.7." (PMID 35008799, 2021). "We also emphasize the importance of PTPRA and CDKN3, which are promising to assess tumor progression in early and advanced stages of the GC, without differentiating the histological types." (PMID 33351778, 2020). "CDKN3 and PTPRA were expressed in tumor tissue samples from patients of both genders." (PMID 33351778, 2020). "In addition, differential analysis from the ONCOMINE online database of tumor and normal tissue in two cohorts indicated that ZWINT, PRC1, CDKN3, CDK1 and CCNA2 were highly expressed in ACC samples." (PMID 31572440, 2019). "However, there was no conspicuous change in CDKN3 expression was observed between the normal tissues and the tumor tissues of CESC, PAAD, and PCPG." (PMID 38720365, 2024). "On the contrary, CDKN3 was reported as a tumor suppressor in some cancers as it is a negative regulator of Cyclin-dependent kinases (CDK1 and CDK2) but the exact effect of CDKN3 in cancer cell proliferation, either enhancing or precluding, it cannot be explained by its CDK regulation, alone." (PMID 35446856, 2022). "However, bioinformatics analysis for identification of molecular target genes in HCC revealed that the relative expression levels of CDKN3 were significantly upregulated in tumor tissues, which proved that our results were not accidental." (PMID 31886176, 2019). "Although we could not explored the CDKN3 protein in tumor samples using western blotting, the cell line data and predominance of the wtCDKN3 mRNA variant in tumors suggests that it was the wt CDKN3 protein that dominated in the CC samples and cell lines." (PMID 26372210, 2015). "However, we do not know whether the effect of CDKN3 on the inhibition of cell proliferation in vitro, would be reflected in reduction of tumor growth in a mouse model." (PMID 26372210, 2015).
tumor (continued). "Further analysis of the model genes within MOCM across pan‐cancer settings revealed that ANLN, CCNB1, CDKN3, EXO1, GJB3 and RAD51AP1 were predominantly overexpressed in tumour tissues, while GGT6 and CYP4B1 were highly expressed in normal tissues." (PMID 38958523, 2024). "CDKN3 is a relatively unique member of the CDKN family because overexpression of CDKN3 has been proven to be oncogenic in multiple cancer types 41, unlike the tumor suppressive CDKNs, such as CDKN1A and CDKN1B." (PMID 38356706, 2024). "The relative expression levels of CDKN3, MKI67, CEP55, SPAG5, AURKA, TOP2A were consistent with the results of bioinformatics analysis (P < 0.05), while the expression levels of UBE2C, CHEK1 and BIRC5 in tumor samples were not significantly different from adjacent normal samples." (PMID 35178291, 2022).
cancer (84 papers, 1997 to 2025). A tumor composed of atypical neoplastic, often pleomorphic cells that invade other tissues. "This comprehensive approach aimed to elucidate the potential molecular mechanisms underlying the involvement of CDKN3 in cancer pathogenesis or clinical prognosis." (PMID 38720365, 2024). "We delved further into the association between CDKN3 expression and overall survival (OS) in 33 distinct cancers." (PMID 38720365, 2024). "CDKN3 has been implicated in various cellular processes, including cell proliferation, cell migration, and cancer development." (PMID 38674285, 2024). "Associations between BRCA1, MCM1, and CDKN3 as the other three potential targets of miR-146a-5p and tumorigenesis were already reported for other cancers." (PMID 26859141, 2016). "Importantly, it was discerned that high level of CDKN3 was associated with shorter OS in these particular cancer types." (PMID 38720365, 2024). "In addition, infiltration of CD4 + T cells, cancer-associated fibroblasts, macrophages, and endothelial cells were associated with CDKN3 expression in various tumors." (PMID 38720365, 2024). "The association of CDKN3 with decreased survival of CC patients and cancer cell proliferation clearly indicate that this gene might be involved in CC progression." (PMID 26372210, 2015). "Deregulation or mutation of CDKN3 has been associated with a variety of human cancers, but it is unknown whether it plays a role in Bcr-Abl-induced tumorigenesis." (PMID 25360622, 2014). "Abnormal expression of CDKN3 is associated with a broad spectrum of human cancers." (PMID 25360622, 2014). "Furthermore, high expression of CDKN3 was associated with poor survival of cancer patients; therefore, it also could be used as a survival marker." (PMID 23405241, 2013). "Analysis of mRNA expression in TCGA paired samples revealed notably enhanced levels of LDHA, SHC1 and CDKN3 in cancer tissues compared to adjacent tissues, whereas PCSK9, BTK, CAV2 and PDGFB showed significantly reduced expression." (PMID 40182622, 2025). "Several recent studies have reported that CDKN3 plays a regulatory role in the survival and proliferation of cancer cells." (PMID 40302936, 2025). "After silencing the expression of CDKN3, the growth and colony formation ability of cancer cells were significantly inhibited." (PMID 40302936, 2025). "CDKN3, a cyclin-dependent kinase inhibitor, is usually high-expressed and regarded as a novel markers in several kinds of cancers." (PMID 38345559, 2024). "In this study, we conducted an analysis of TCGA_GTEx data obtained from UCSC to explore the expression of CDKN3 in pan-cancer." (PMID 38720365, 2024). "The authors further showed that knockdown of CDKN3 expression resulted in reduced cancer metastasis and adhesion." (PMID 38356706, 2024). "In our study, we examined the expression of CDKN3 across various types of cancer using a pan-cancer analysis encompassing multiple databases." (PMID 38720365, 2024). "Heatmaps were used to illustrate the associations between CDKN3 expression and CD4 + T cells, cancer-associated fibroblasts, macrophages, and endothelial cells." (PMID 38720365, 2024). "Our pan-cancer analysis conducted in the study provides a comprehensive understanding of the involvement of CDKN3 gene in tumorigenesis." (PMID 38720365, 2024). "CDKN3 promotes cancer growth via regulating cell cycle and DNA replication signaling, and inhibition of CDKN3 reduces cell proliferation, invasion and promotes apoptosis in cancer cells." (PMID 38345559, 2024). "Overexpression of CDKN3 is reported as a predictor of poor survival and promotor of proliferation and migration in many cancers including BC." (PMID 38745208, 2024). "The protein expression levels of PLK1, SLC2A1, ANGPTL4, and CDKN3 in LUAD tissues were all significantly higher than those in para-cancer tissues." (PMID 38345559, 2024).
cancer (continued). "Using bioinformatics tools such as The Cancer Genome Atlas (TCGA) and the UCSC Xena database, a comprehensive pan-cancer analysis of CDKN3 was conducted." (PMID 38720365, 2024). "The role of cyclin-dependent Kinase Inhibitor 3 (CDKN3) in promoting human tumors were reported in the literature review and pan-cancer analysis." (PMID 39689117, 2024). "The correlation between high CDKN3 expression and reduced survival rates emphasizes the importance of this gene as a potential target for cancer therapy." (PMID 38674285, 2024). "Our exploration yielded compelling insights, revealing distinct associations between CDKN3 expression and DSS in a range of cancer types." (PMID 38720365, 2024). "The dysregulation of CDKN3 can lead to uncontrolled proliferation and contribute to cancer development." (PMID 38674285, 2024). "High levels of mitotic CDKN3 expression is the most likely mechanism for frequent CDKN3 mRNA over-expression in human cancer." (PMID 37007961, 2023). "There is increasing evidence that cyclin-dependent kinase inhibitor 3 (CDKN3) has significant regulatory roles in cancer development." (PMID 37682177, 2023). "A pan-cancer analysis has been conducted to evaluate the expression of CDKN3 in comparison to the corresponding normal tissues in the TCGA database." (PMID 37682177, 2023). "CDKN3 downregulation is involved in the formation of a hypoxic microenvironment by inhibiting the proliferation and invasion of cancer cells." (PMID 36140669, 2022). "Then, a prognostic index for all cancer was constructed by the formula MRG = expression level of BIRC5 × (−0.4126) + expression level of PLK1 × 0.39986 + expression level of CDKN3 × 0.2651 + expression level of CYP4B1 × (−0.0955)." (PMID 36293001, 2022). "Among them, CDKN3 plays a key role in promoting cancer by affecting the cell cycle, which is closely related to the occurrence and development of HCC." (PMID 32000807, 2020). "It had been reported that the overexpression of CDKN3 was correlated with the poor survival in cancer patients." (PMID 31043166, 2019). "Excessive replication of the centrosome is considered to be a common feature of almost all human cancers, and CDKN3 happens to have the ability to prevent this abnormality." (PMID 31886176, 2019). "To validate our findings, we conducted a study of the literature by randomly selecting five genes (DBF4, MCM2, ID3, EXOSC4, and CDKN3) from the 565 potential cancer genes." (PMID 25866773, 2015). "We also found that inactivation or partial inhibition of CDKN3 gene expression dramatically decreases cancer cell proliferation in vitro." (PMID 26372210, 2015). "Overexpressed in several kinds of cancers, cyclin-dependent kinase inhibitor 3 (Cdkn3) dephosphorylates and prevents CDK2 kinase activation in a cyclin-dependent manner." (PMID 25505565, 2013). "However, researches on CDKN3 has been limited to a few cancer types, leaving its role in other cancers ambiguous." (PMID 38720365, 2024). "In addition, we also observed that genes contributing to cancer cell stemness, such as CDKN3, BRIX1, TBCA, TMX2, and others, were highly expressed in the Luminal A DAB2IP-low tumors compared with the DAB2IP-high Luminal A tumors." (PMID 39418101, 2024). "Moreover, we examined the protein expression levels of the four ARGs (PLK1, SLC2A1, ANGPTL4, CDKN3) in cancer tissues and para-cancer tissues from clinical LUAD patients." (PMID 38345559, 2024). "Here, several growth-associated genes were up-regulated, including RNA helicase (HELLS), PRR11, CDCA8, and DNA topoisomerase 2 (TOP2A), HMGB2, EIF2B4, and CDKN3, which are thought to serve important functions during growth stimulation, many of which are known to be up-regulated in various cancers." (PMID 37907238, 2024). "In these specific cancers, elevated CDKN3 expression was conspicuously correlated with poorer DSS." (PMID 38720365, 2024).
cancer (continued). "CDKN3, CKS2 and MNAT1 consist of serine/threonine kinases crucial for regulating cell cycle transition and are significantly implicated in the pathogenesis of numerous cancers." (PMID 39689117, 2024). "In summary, we conducted a comprehensive pan cancer study on CDKN3." (PMID 38720365, 2024). "The levels of CDKN3 and macrophage infiltration vary among different types of cancer." (PMID 38720365, 2024). "The research emphasized the role of CDKN3 in pan cancer analysis." (PMID 38720365, 2024). "CDKN3 has also been investigated in cancers of neuronal origin." (PMID 38356706, 2024). "Previous studies have reported different expression patterns of CDKN3 in several types of cancers." (PMID 37682177, 2023). "Abnormal expression of CDKN3 is seen in many types of cancer." (PMID 37489460, 2023). "Thus, CDKN3 mainly inhibits the transition from the G 1 to the S phase, and plays an important role in inhibiting cancer progression." (PMID 32000807, 2020). "However, because CDKN3 is over-expressed in cancer cells, it is expected that its effect in normal cells would be minimal." (PMID 26372210, 2015). "However, appropriate clinical trials should investigate the clinical value of measuring CDKN3 mRNA as an indicator for additional neoadjuvant chemotherapy or specific target cancer therapy." (PMID 26372210, 2015). "To investigate whether this gene is essential for proliferation, migration, and invasion of cancer cells, we inhibited CDKN3 gene expression in cell lines derived from CC (HeLa, CaSki, SiHa) using specific siRNAs." (PMID 26372210, 2015). "Moreover, CDKN3 levels were increased compared to adjacent para-carcinoma tissues." (PMID 37682177, 2023). "Furthermore, CDKN3 was reported to be downregulated or upregulated in various cancers." (PMID 35446856, 2022). "Clearly, CDKN3 seems to be a target in CC, but further study is needed to identify or develop either a small molecule drug that inhibits CDKN3 function specifically in neoplastic cells or an effective systemic delivery strategy to introduce CDKN3-specific siRNAs into cancer cells." (PMID 26372210, 2015). "To investigate the relationship between CDKN3 and the immune microenvironment in pan-cancer, we conducted an analysis using the GEPIA2 database to assess the correlation between CDKN3 expression and immune cells." (PMID 38720365, 2024). "A literature survey about significant biomarkers highlighted in survival analysis revealed that GNG11, CBX2, CDKN3, ARHGEF10, CLN8, SEC61G and PTDSS1 genes present similar survival and prognostic behaviors in the specified cancers." (PMID 37489460, 2023). "The results indicated that the mRNA levels of ANLN, ARNTL2, CDKN3, and FAM53B in the cancer cell lines (SW 1990, BxPC-3, CFPAC-1, and PANC-1) were significantly higher than those in the normal cell line (HPDE), indicating their prognostic value." (PMID 35864471, 2022). "CDKN3 is a dual-specificity protein tyrosine phosphatase of the CDC14 group, which is often overexpressed in human cancers." (PMID 30517191, 2018). "For further exploration, we selected five genes that have been previously experimentally demonstrated in other cancer setting in humans, CXCL8/IL8, UHRF1, BRCA1, MCM10, and CDKN3." (PMID 26859141, 2016). "There is currently no comprehensive study evaluating the prognostic value of CDKN3 in various cancers." (PMID 38720365, 2024). "In addition, the expression levels of ANLN, ARNTL2, CDKN3, and FAM53B were upregulated in cancer tissues from our cancer center." (PMID 35864471, 2022). "Unfortunately, the protein expression levels of CDKN3 were not explored because of pending cancer tissue analysis in the HPA database." (PMID 34596112, 2021).
cancer (continued). "Indeed, of the eight CRC GWAS loci found within this subset of CRC-related smoking genes, CDCA8, CDKN3, FADS1, FADS2, MYBL2, PCSK9, and PRC1, have all been reported to be overexpressed in others cancers and to play important roles in the DNA damage response pathway." (PMID 37509213, 2023). "It is not known whether this relocation of CDKN3 to the cytoplasm is related to the viral proteins or is a regulatory mechanism of cancer cells that confers a growth selective advantage." (PMID 26372210, 2015). "Although CDKN3 has a negative adjustment effect on CDK1 and CDK2, the carcinogenic effect of CDKN3 is abnormally expressed, which is related to a variety of human cancers." (PMID 36147496, 2022).
infection (7 papers, 2010 to 2023). The state of being infected such as from the introduction of a foreign agent such as serum, vaccine, antigenic substance or organism. "Lastly, the CDK2 inhibitor, Cdkn3 also accumulated late in infection." (PMID 38107402, 2023). "Interestingly, transcript levels of genes regulating DNA replication and cell cycle progression (Cdc25c, Fosb, Cdkn3, cyclin E2, Chaf1b, Cdt1) were specifically increased in SkMCs and neurons after infection." (PMID 28775382, 2017).
CDKN3 also shares sentences with these, for which no sentence is quoted: acute myeloid leukemia (3 papers); bladder cancer (3); neuroendocrine tumors (3); adenocarcinoma of the rectum (2); astrocytoma (2); breast tumor (2); cholangiocarcinoma (2); endothelial dysfunction (2); meningioma (2); multiple myeloma (2); osteosarcoma (2); prostate adenocarcinoma (2); psoriasis (2); Rb (2); sarcoma (2); type 2 diabetes (2); Alzheimer disease (1); anaplastic oligoastrocytoma (1); atherosclerosis (1); Barrett adenocarcinoma (1); bladder tumors (1); bladder urothelial carcinoma (1); bronchogenic carcinoma (1); cardiac hypertrophy (1); chronic liver failure (1); colitis (1); colorectal NETs (1); coronary heart disease (1); diabetic kidney disease (1); digestive system carcinoma (1).
A further 34 diseases each share a sentence with CDKN3 in 1 paper.